STAT1 (signal transducer and activator of transcription 1)
Diseases named in the same sentence as STAT1 in open-access papers (continued):
Sharing a sentence is not in itself a finding about the gene and the disease.
tumor (continued). "IHC analysis further demonstrated a significant reduction in the positive rates of G3BP1 expression and upregulation in the positive rates of STAT1 expression within tumor tissues in the BIN1-WT + sh-G3BP1 group compared to the BIN1-WT group." (PMID 40346580, 2025). "While multiple studies have examined IRF8 to have important roles in the context of myeloid cells and its tumor suppressor function through downstream STAT1 signaling, there has been limited studies of the role of IRF8 in cytotoxic T cells." (PMID 40610421, 2025). "STAT1 regulates immune responses by activating genes involved in defense against pathogens and anti‐tumor immunity." (PMID 40287845, 2025). "Here we show that hexokinase domain component 1 (HKDC1) promotes tumor immune evasion in a CD8+ T cell-dependent manner by activating STAT1/PD-L1 in tumor cells." (PMID 38351096, 2024). "EGCG significantly inhibited the expression and activity of IDO and suppressed IDO-mediated tumor immune escape by blocking the IFN-γ-triggered JAK-PKC-δ-STAT1 signaling pathway." (PMID 39765834, 2024). "Further analysis of a whole-cell tumor challenge affirmed these findings, as spontaneous tumor growth was more rapid in STAT1−/− mice." (PMID 38675812, 2024). "Activation of the IFN‐γ/STAT1 pathway can also suppress tumor cell proliferation and induce tumor dormancy." (PMID 39003635, 2024). "It was shown that STAT3 and STAT5 are involved in tumor initiation and progression, while STAT1 and STAT2 play an essential role in anti-tumor defense and long-term immune response." (PMID 39136000, 2024). "Phosphorylation of STAT1 impedes tumor growth, whereas STAT3 and STAT5 play roles in the initiation and development of tumors." (PMID 38338162, 2024). "The tumor growth curve demonstrated that vaccinated STAT1−/− mice exhibited significantly slower tumor progression than the unvaccinated STAT1−/− mice." (PMID 38675812, 2024). "Here we reveal a tumor-extrinsic role of TP63 in promoting immune evasion of SCC cells by suppressing the IFNγ-STAT1 signaling." (PMID 38509096, 2024). "In response to cytokines, STAT1 functions as a tumor suppressor or tumor promoter in various cancer types." (PMID 38985127, 2024). "In this work, we use clinical HCC samples and a series of HCC preclinical models to demonstrate the role of HKDC1 in promoting tumor immune evasion by coupling STAT1 activation with the cellular cytoskeleton to enhance PD-L1 expression in HCC cells." (PMID 38351096, 2024). "It regulates the expression of cyclin-dependent kinase inhibitor 1 (P21) by activating STAT1 in tumour cells." (PMID 38496017, 2024). "Among others, nuclear Hpa2 elicited the interferon response, a well-established anti-tumor pathway, best exemplified by a prominent increase of STAT1 phosphorylation in Hpa2-Nuc tumors." (PMID 38519456, 2024). "The TRIB3/STAT1/CXCL10 axis modulated the infiltration abundance of CD 8+ T cells in tumor tissues, leading to the immune escape phenomenon." (PMID 38604154, 2024). "The TRIM65-JAK1/STAT1 axis is used by tumor cells to inhibit M1 macrophage polarization and promote tumor growth." (PMID 38542388, 2024). "Some studies have found that TH1 cells can promote anti-tumor immune responses, reduce cancer cell proliferation, and guide them into a dormant state by activating the STAT1 signaling pathway." (PMID 39139574, 2024). "It is important to clarify this distinction because STAT1 expression impacts the host immune system and tumor microenvironment differently." (PMID 38675812, 2024). "Tumor-infiltrating lymphocytes and other immune effectors secrete cytokines such as TNFα and IFNγ, which can activate NFκB and STAT1 signaling in cancer cells." (PMID 39461475, 2024). "Our data defines IFITM3-mediated Treg suppression function in a mice tumor model and highlights the correlation between STAT1 and IFITM3 regulation in TI-Treg cells." (PMID 38167862, 2024).
tumor (continued). "STAT1, however, is crucial in NK cell development, IFNγ production, and cytotoxic function, particularly in the tumor microenvironment." (PMID 39349746, 2024). "In summary, this study revealed that DHM exerts therapeutic effects on MM by inhibiting viability, migration, invasion, EMT, and tumor growth, as well as enhancing apoptosis via STAT1/RIG-I activation." (PMID 39055888, 2024). "STAT1, a key transcription factor shaping the tumour microenvironment, is also upregulated in both the tumour and stromal compartments of p16+/HPV+ tumours." (PMID 39328208, 2024). "IFN‐induced PD‐L1 expression is regulated by the STAT1 signalling cascade in both macrophages and tumor cells." (PMID 39564003, 2024). "The results indicated that STAT1−/− induces robust tumorigenesis, yet a controlled tumor response was attained upon CRT/E7 vaccination." (PMID 38675812, 2024). "Tumour cells showed clear separation of Kmt2c and Kmt2d KO from WT, and differential gene expression (DGE) analysis identified Ly6a, Bst2, Ifi27l2a and Stat1 as the top highly upregulated genes in both KO tumour cells compared with the WT." (PMID 38926506, 2024). "Biomechanical forces promote tumor stemness through integrin-cytoskeletal prestress-AIRE signals while mediating the quiescence of stem-like tumor cells through DDR/STAT1/P27 signaling." (PMID 39430235, 2024). "The effects of nivolumab on the tumor cells were minor, with only STAT1 showing significant up-regulation." (PMID 39475596, 2024). "Taken together, these results suggest that macrophage polarization in the LGG TME can be driven by interferon-gamma activation of the STAT1/IRF1/IRF5 to promote tumor progression in concert with TGFB2 levels." (PMID 38539537, 2024). "Recent studies have highlighted the important role of STAT1 in PD-L1-induced tumor immune evasion under IFNγ stimulation." (PMID 38351096, 2024). "From our data, IFITM3 suppresses the transcription function and protein stability of STAT1 to maintain Treg function in the tumor microenvironment." (PMID 38167862, 2024). "STAT1 is a TF overexpressed in OC and can act as oncogene or tumor suppressor depending on the disease stage and tissue heterogeneity, whereas OAS1 was shown to be upregulated in several cancers to promote tumor anti-viral responses." (PMID 39634630, 2024). "Collectively, this study first revealed that DHM can restrain EMT and tumor growth in MM by activating STAT1/RIG-I signaling, which provides a novel drug for the treatment of MM." (PMID 39055888, 2024). "Otherwise, DHM was found to exert inhibitory effects on EMT and tumor growth by activating the STAT1/RIG-I pathway in MM." (PMID 39055888, 2024). "High expression of STAT1 generally confers good prognosis in solid tumors through promotion of anti-tumor immunity." (PMID 38424636, 2024). "Levels of pSTAT3 were relatively maintained in the tumor, whereas p-STAT1 levels peak between days 9 - 21 post-IRE treatment, consistent with the changes in IFN-γ." (PMID 38711517, 2024). "In contrast, STAT1−/− mice exhibited significantly greater and sustained spontaneous tumor growth compared to the control group." (PMID 38675812, 2024). "The active form of STAT1 then translocates to the nucleus, where it acts as a transcription factor regulating various aspects of tumor suppression, including cell grown arrest, apoptosis, and inhibition of angiogenesis." (PMID 38990440, 2024). "High levels of CXCL8 have been found to induce epithelial-mesenchymal transition and promote the proliferation, migration and invasion of tumor cells through the JAK/STAT1/HIF-1α/Snail pathway." (PMID 39488622, 2024). "IL-10 can enhance the immune response and promote anti-proliferative and pro-apoptotic pathways by activating the STAT1 pathway in tumor-resident cells CD8+T." (PMID 39591319, 2024).
tumor (continued). "After confirming the activation of STAT1 signaling in tumor endothelial cells after ACT, we further analyzed endothelial cells by CD31 immunofluorescence imaging of the harvested tumors." (PMID 39629126, 2024). "For example, TGF-β1 can act as a protein kinase, induce PKM2 and then activate the PKM2/STAT1-PD-L1 axis, which promotes the process of tumor glycolysis, remodels the immune microenvironment, and promotes tumor proliferation, migration and invasion." (PMID 39816354, 2024). "IFN-γ induces PD-L1 transcription in tumor cells by increasing the acetylation of the PD-L1 promoter and the phosphorylation of STAT1 at Tyr701." (PMID 38539913, 2024). "In the immune exclusion tumour area, STAT1 and STAT2 from the STAT family showed increased regulon activities, which contribute to the promotion of proliferation, survival, angiogenesis and immunological escape." (PMID 39187937, 2024). "Blocking the inflammatory cytokine IFNγ or directly depleting STAT1-IFITM3 axis phenocopies the restored suppressive function of tumor-infiltrating Tregs in the tumor model." (PMID 38167862, 2024). "At the same time, we found that the expression levels of phosphorylated STAT1 significantly decreased in tumor tissues treated simultaneously with anti-mouse IFN-γ antibody, Efm, and sorafenib compared to the group not treated with anti-mouse IFN-γ antibody." (PMID 39353096, 2024). "EGCG suppresses IDO-mediated tumor immune escape by blocking the IFN-γ-triggered JAK-PKC-δ-STAT1 signaling pathway, which is considered to be a potential immunological and targeted therapeutic agent." (PMID 39765834, 2024). "All unvaccinated STAT1−/− mice died within 21 days of tumor formation, whereas two vaccinated STAT1−/− mice survived until the experimental endpoint." (PMID 38675812, 2024). "Intriguingly, cluster 6, which exhibited moderate differentiation state, was found highest expression level of transcription factors STAT1/STAT2-IRF9/IRF1 activated by interferon gamma (IFN-γ) leading to upregulation of tumor PD-L1 expression following RT." (PMID 38528587, 2024). "Firstly, our tumor experiments were conducted in hosts with inherent STAT1−/−, so the STAT1 expression in the tumor microenvironment remained unaltered." (PMID 38675812, 2024). "Enhancement of CD8+ TCM cell differentiation determined by Stat-1, is dependent on the tumor-draining lymph nodes (TDLN) but takes place in peripheral blood, with metabolic remodeling of CD8+ T cells lasting the entire course of the the combination therapy." (PMID 38821965, 2024). "Here, we identified a negative feedback loop in which reduced IFITM3 expression induces higher phosphorylation of STAT1, which promotes IFNγ responses in tumor-infiltrating Treg cells (TI-Tregs) and induces the fragility of TI-Tregs." (PMID 38167862, 2024). "Expression of type I IFNs and activation of IFNAR/STAT1 induces the expression of multiple effectors, including pro-apoptotic and anti-proliferative genes, that are detrimental to tumor cell survival." (PMID 39295867, 2024). "Previous research showed that the STAT1/RIG-I axis has significant implications for tumor development and pathogenesis." (PMID 39055888, 2024). "On the contrary, knocking out both IFITM3 and STAT1 in TI-Tregs restores the suppression function and inhibits the anti-tumor response." (PMID 38167862, 2024). "On the other side, CD8+ T cells release the inflammatory factor IFN-γ, which induces the phosphorylation of STAT1 by transmitting signals into tumor cells through its receptor in the TIME." (PMID 38882349, 2024). "This is due to the ability of IFN-γ to activate the JAK-STAT1 signaling pathway in tumor cells, enhance the binding of STAT1 to the SLC7A11 transcription start site, and down-regulate the expression of Xc- system." (PMID 39359721, 2024). "The absence of IL-17 has been shown to hinder the activation of the STAT1 pathway, resulting in accelerated tumor progression." (PMID 39906741, 2024).
tumor (continued). "IFN-γ production, STAT1 induction in its targets, and subsequent changes, especially in vasculatures in the tumor, were examined." (PMID 39629126, 2024). "The analysis of IRFs and STATs in total tumor tissues showed that IFNΒCOL01 therapy led to elevated STAT1, 2 and 6 levels and expression of all IRFs." (PMID 38995014, 2024). "We further validated that the representative core genes in the IL-6/JAK/STAT3 pathway (Il6st (Gp130), Fas and Stat1) and the late response of estrogen (St6gal, Areg and Serpina3) were highly reduced in shMCT-1 tumor when compared to scramble tumor." (PMID 38505617, 2024). "This tumor-suppressive effect was achieved by promoting the activation of M1 macrophages via STAT1 signaling pathway." (PMID 38992114, 2024). "It is established that the downregulation of STAT1 activation and the reduction in its expression are prevalent in various tumoral cells." (PMID 38990440, 2024). "In order to shed light on this question, a 4-gene inflammatory signature comprised of CD8A, STAT1, LAG3, and CD274 (encoding PD-L1) was assessed by the RNA-sequencing of the baseline tumor samples of patients included in the CheckMate-816 study." (PMID 39123401, 2024). "STAT1 has traditionally been regarded as a tumor-suppressor, inhibiting angiogenesis and metastasis, while promoting apoptosis and enhancing immunosurveillance." (PMID 38750462, 2024). "Disrupting this circuit genetically, either by knocking out IFITM3 or STAT1, has therapeutic efficacy in tumor models by abolishing the function of TI-Tregs." (PMID 38167862, 2024). "Tumor-derived IFN favors the expression of PDL1 in tumor cells via IFNAR1/STAT1 and PD1 in immune cells, resulting in immune suppression in head and neck malignancies (HNSCCs)." (PMID 38672681, 2024). "Single checkpoint inhibitor therapies or combined with APG‐157 or double immunotherapy decreased p‐STAT1 and PD‐L1 expression (in these blots, resected samples represent both the tumor, stromal and immune cells in the TME)." (PMID 38686626, 2024). "Our results confirmed that vaccinated STAT1−/− mice managed to slow tumor growth, while vaccinated control mice prevented tumor growth." (PMID 38675812, 2024). "Our data establish a previously unappreciated mechanism by which HKDC1 couples the cytoskeleton to STAT1/PD-L1-mediated tumor immune evasion." (PMID 38351096, 2024). "Given the controlled tumor response observed in STAT1−/− mice, it is critical to examine the immunological response elicited by CRT/E7." (PMID 38675812, 2024). "F2RL1 encodes PAR2, a G-protein-coupled receptor known to downregulate type I IFN responses and STAT1 signaling 62, leading to the polarization of macrophages towards an M2-like, tumor-promoting phenotype 63." (PMID 38577601, 2024). "In support of this notion, our integrated epigenetic and machine learning analyses, extracted from bone marrow–derived patient tumor samples, also support a critical role for STAT1 in governing surface CD38." (PMID 40453054, 2024). "Some functions of these highly expressed miRNAs have been studied, where miR-584-5p targets some tumor suppressor genes including STAT1, PTEN, and cyclin D181." (PMID 38632250, 2024). "At the same time, STAT1 is an important member of the classical tumor regulatory signaling pathway JAK/STAT pathway and is also closely related to the ERK pathway." (PMID 36899018, 2023). "Previous studies have shown that the deletion of PTPN2 in tumor cells can enhance anti-tumor immunity by promoting IFN/JAK/STAT-1 signaling to drive T cell recruitment and MHC-I-dependent antigen presentation." (PMID 37500611, 2023). "IL-27 exerts many of its anti-tumor effects via STAT1 mediated signaling, indicating that the delivered IL-27 is bioactive." (PMID 37842640, 2023). "We then assessed STAT1 activity in tumor-bearing mice treated with CAR4 T cells or control CD4+ T cells (CTRL4)." (PMID 37248395, 2023).
tumor (continued). "In this scheme, classic M1 macrophages are defined by the expression of the transcription factor, STAT1, and lead to an anti-tumor response via the presentation of tumor antigens to adaptive immune cells." (PMID 37444590, 2023). "In tissue specimens collected from a local cohort of patients, STAT1 was characterized as an upregulated protein in tumor tissues compared with normal tissues." (PMID 36899018, 2023). "As an active form of STAT1, p-STAT1 has been shown to inhibit tumor growth by regulating cell cycles." (PMID 36915717, 2023). "In conclusion, the present study identified a novel anti-tumor effect of butyrate, which exerts by suppressing PD-L1 transcription via STAT1 acetylation, providing scientific information to understand the pivotal role of butyrate in tumor immunity." (PMID 37931529, 2023). "Taken together, we concluded that a tumor sample with high STAT1, STAT2, STAT4, and STAT5B expression levels tended to be enriched in T cell dysfunction phenotypes, while STAT6 showed to be the opposite." (PMID 36968603, 2023). "Silencing RHAMM expression by siRNA knockdown in Py8119 MMTV-PyMT tumor cells also reduces STAT1 protein expression (Western blot)." (PMID 37349798, 2023). "Our results highlight a critical role for tumor acidosis in the IFN-γ-mediated induction of PD-L1 expression via enhanced STAT1 phosphorylation and subsequent immune escape of anti-PD-L1 responsive tumors." (PMID 38102680, 2023). "Reduced tumor cell expression of STAT1 has been observed in many cancer types such as melanoma and chronic myeloid leukemia." (PMID 38022653, 2023). "Modulating the STAT1 signaling pathway in tumor-infiltrating myeloid cells fine-tunes the anti-cancer immunity of TIME to maximize the therapeutic efficacy of anti-PD1 for TNBC." (PMID 37055410, 2023). "Mechanistically, MFAP5 deficiency in CAFs downregulates HAS2 and CXCL10 via MFAP5/RCN2/ERK/STAT1 axis, leading to angiogenesis, hyaluronic acid (HA) and collagens deposition reduction, cytotoxic T cells infiltration, and tumor cells apoptosis." (PMID 37156839, 2023). "The increase in PD-L1 expression by IFN-γ is transcriptionally regulated through activation of STAT1 in tumor cells." (PMID 37731735, 2023). "Then, the release of FEGCG and MPI can not only regulate PD-L1 signaling with IRF, STAT-1/pSTAT-1, and PD-L1 expression, but also induce apoptosis signaling with Bcl-2 and Bax expression in tumor cells." (PMID 37277118, 2023). "In the context of cancer, including tumors with CIN, STAT1 has generally been shown to exert tumor suppressor properties." (PMID 37561163, 2023). "STAT1 carries out its tumour suppressor role by inducing gene expression of proteins involved in cell growth arrest, apoptosis, and angiogenic inhibition." (PMID 36579897, 2023). "Although STAT1 is commonly regarded as a tumour suppressor, several studies have highlighted its oncogenic role in the pathogenesis of tumours." (PMID 37865727, 2023). "Ptpn2-mediated dephosphorylation of Stat1 and Jak1 negatively regulates signaling induced by IFNγ, a potent inhibitor of tumor growth via stimulation of the antitumor immune response." (PMID 36968224, 2023). "Next, we designed a sequential treatment regimen of CXCL16 NAb and STAT1 inhibitor to test possible enhanced efficacy of sensitizing MCT-primed tumor to anti-PD-1 treatment." (PMID 37055410, 2023). "Mechanistically, tumor cell-intrinsic STAT1-mediated tumor suppression is due to its antiproliferative effects via cell cycle inhibition and induction of cell death." (PMID 37561163, 2023). "As a tumor suppressor miRNA, miRNA203 has been reported to target signal transducer and activator of transcription -1(STAT1)." (PMID 37587273, 2023). "Consistent with the in vitro cell experiments, we observed that PTP 9 and anti-PD-1 cotreatment induced a significant increase in tumor expression of Cxcl11, Ccl5, Stat1, Stat3, Tap1, Irf1, Casp8, and Pdl1, compared with anti-PD-1 treatment alone." (PMID 36968224, 2023).